CGAS (cyclic GMP-AMP synthase)
Diseases named in the same sentence as CGAS in open-access papers (continued):
Sharing a sentence is not in itself a finding about the gene and the disease.
cardiovascular diseases (continued). "This review focuses on that cGAS-STING-mediated inflammatory response in the progression of cardiovascular diseases and the prospects of cGAS or STING inhibitors for treatment of cardiovascular diseases." (PMID 36072862, 2022). "Recently, it has been reported that cyclic GMP-AMP synthase (cGAS) stimulator of interferon genes (STING) signaling pathway was associated with the occurrence and development of cardiovascular diseases." (PMID 34483919, 2021). "This study suggests a connection between the radiation-induced DNA damage and the induction of inflammation which supports the inhibition of the cGAS-STING pathway in the prevention of radiation-induced cardiovascular disease." (PMID 33114474, 2020). "The effects of cGAS-STING activation are central to many cardiovascular disease processes." (PMID 39861173, 2025). "Understanding the role ofthe cGAS-STING pathway in the cardiovascular system provides insights into thepathogenesis of cardiovascular diseases and may offer potential therapeutictargets for intervention." (PMID 39076568, 2024). "Further research with PF-06928215 may make it possible to treat cardiovascular diseases through inhibition of the cGAS-STING signaling pathway." (PMID 38720328, 2024). "Overall, cGAS inhibitors demonstrate protective effects in cardiovascular diseases." (PMID 38803502, 2024). "In cardiovascular disease, mitochondrial dysfunction leads to the release of mtDNA into the cytoplasm, triggering cGAS, subsequently activating the STING signaling pathway and eliciting the release of inflammatory mediators that exacerbate cellular damage and inflammatory response." (PMID 38419127, 2024). "The connection between cardiovascular diseases and the cGAS-STING pathway." (PMID 38803502, 2024). "Therefore, the application of cGAS or STING inhibitors will provide a new strategy for the treatment of cardiovascular diseases." (PMID 36072862, 2022). "CGAS-STING signaling participated in the development of multiple sterile cardiovascular diseases." (PMID 36072862, 2022). "Our findings suggested that the cGAS-STING pathway may be a novel target for the prevention of age-related cardiovascular disease." (PMID 36465181, 2022). "Therefore, targeted inhibition of cGAS or STING provides new avenues for the treatment of cardiovascular diseases." (PMID 36072862, 2022). "Thus, the cGAS-STING pathway may be a potential target for the prevention of cardiovascular diseases in the elderly." (PMID 36465181, 2022). "Overall, the cGAS‐STING pathway plays a complex and multifaceted role in cardiovascular diseases, driving both harmful inflammation and essential cellular functions." (PMID 39158380, 2025). "The DDR pathways, particularly the CGAS-STING1 pathway, have been targeted, mostly through genetic and to a lesser degree through pharmacological interventions, in mouse models of cardiovascular diseases." (PMID 40180542, 2025). "Overall, many lines of evidence highlight DDX41 as an upstream sensor of the cGAS‐STING pathway, implicating its relevance in cGAS‐STING‐dependent regulation of metabolic and cardiovascular diseases." (PMID 39158380, 2025). "Recent studies have demonstrated that modulating the cyclic GMP-AMP synthase (cGAS)/stimulator of interferon genes (STING) pathway would influence cell senescence in neurodegeneration and cardiovascular disease in elderly individuals." (PMID 39846254, 2025). "The activation of cGAS-STING by mtDNA and other substrates has manifested clinically in many cardiovascular diseases." (PMID 39861173, 2025). "Hence, we postulate that there is a complex relationship between the cGAS-STING and PERK-eIF2α pathways and that, through convergent downstream signaling, they may collaboratively contribute to the pathophysiology of cardiovascular diseases (CVDs) via the cGAS-STING/PERK-eIF2α signaling axis." (PMID 39664570, 2024).
cardiovascular diseases (continued). "This section will explore the use of cGAS and STING suppressors specifically in the context of cardiovascular diseases, analyzing their potential therapeutic benefits and implications." (PMID 38803502, 2024). "This review delves into recent findings on STING and the cGAS-STING pathways, focusing on their regulatory mechanisms and impact on cardiovascular diseases." (PMID 38803502, 2024). "Since inflammation plays a crucial role in cardiovascular diseases, we further utilized ELISA to measure the levels of IL-6, IL-1β, and TNF-α in the supernatant of cells after cGAS knockdown." (PMID 38124089, 2023). "Considering that cell death is common in cardiovascular diseases and because cell death releases DAMPs, which activates the PRRs, activation of the CGAS-STING1 pathway in cardiovascular disease is not unexpected." (PMID 40180542, 2025). "Treatment effects of PF-06928215 on cardiovascular disease through inhibition of the cGAS-STING signaling pathway have not been studied in vivo." (PMID 38720328, 2024). "Notably, it was observed that, NLRP3 inflammasome activation dependent on cGAS-STING signaling fueled myocardial inflammation and the development of cardiovascular diseases." (PMID 36072862, 2022). "This study supports the recent effort to develop inhibitors of the cGAS-STING pathway as anti-inflammatory agents that could be used in the prevention and alleviation of radiation-induced cardiovascular disease." (PMID 33114474, 2020). "The cyclic GMP-AMP synthase (cGAS)-stimulator of interferon genes (STING) pathway, a pivotal regulator of innate immunity, has been demonstrated to exacerbate inflammation-induced metabolic abnormalities 10 and cardiovascular diseases 11 through its suppression." (PMID 41356195, 2026). "The genetic deletion of key molecules in this pathway, such as CGAS, STING1, and interferon regulatory factor 3, affords salubrious effects, including improving survival and cardiac dysfunction, rendering the CGAS-STING1 pathway an attractive therapeutic target in cardiovascular disease." (PMID 40180542, 2025).
infectious disease (28 papers, 2019 to 2025). A disorder directly resulting from the presence and activity of a microbial, viral, or parasitic agent in humans. "Activation of the cGAS–STING pathway by “self” DNA is also attributed to various infectious diseases and autoimmune or inflammatory conditions." (PMID 37686127, 2023). "As a sensor of cytosolic DNA, cGAS-STING signalling is highly relevant in infectious disease with several examples of the clinical efficacy of STING inhibitors." (PMID 38067135, 2023). "Initially, the cGAS–STING pathway was primarily concerned with immune mechanisms in infectious diseases." (PMID 34906241, 2021). "The findings highlight the dynamic role of gigaxonin in enhancing antiviral innate immune responses by targeting both TREX1 and cGAS, suggesting that targeting gigaxonin may constitute a novel therapeutic approach for combating infectious diseases." (PMID 40936183, 2025). "Impaired DDR can lead to leakage of nuclear DNA into the cytosol, which can trigger the cGAS-STING/ type I interferon antiviral innate immune response — especially following an infectious disease event, which activates the same pathway and heightens cellular stress and DNA damage." (PMID 40894167, 2025). "cGAS, a newly identified cytoplasmic DNA sensor, has been well studied in infectious diseases, but its role during T. gondii infections is unknown." (PMID 37508526, 2023). "In addition, several studies have mentioned the crosstalk between TLR9 and cGAS-STING in response to DNA damage rerated with infectious diseases and some pathological conditions." (PMID 36176986, 2022). "mtDNA stress may contribute to cyclic GMP-AMP synthase (cGAS) stimulator of interferon genes (STING) pathway activation in infectious diseases." (PMID 34016129, 2021). "Deeper insight into these interactions might enable us to clarify the pathogenesis of certain infectious diseases and better harness the cGAS-STING pathway for antimicrobial methods." (PMID 32532954, 2020). "Further studies are needed to explore the direct interaction between TLR and cGAS/STING signaling to understand the immune homeostasis and pathogenesis of inflammatory and infectious diseases." (PMID 38339107, 2024). "The mechanistic and functional comprehension of the interplay between cGAS-STING pathway and pathogens is opening the way for the development and application of pharmacological agonists and antagonists in the treatment of infectious diseases." (PMID 36825026, 2023). "In this review, we briefly summarize the current understanding of DNA sensing through the cGAS-STING pathway and mainly focus on the potent capacity of cGAS-STING signaling pathway in the host immunity against infectious diseases." (PMID 36825026, 2023). "Cyclic GMP‐AMP synthase (cGAS) and stimulator of interferon genes (STING) play critical roles in the innate immunity against infectious diseases and are required to link pathogen DNA sensing to immune responses." (PMID 35635376, 2022). "Therefore, TLRs, through different PAMPs and DAMPs, are critical regulators of cGLRs such as cGAS/STING functioning and inflammatory and infectious diseases." (PMID 38339107, 2024). "Cyclic GMP‐AMP synthase (cGAS) and stimulator of interferon genes (STING) play critical roles in innate immunity against infectious diseases, while the mechanisms that cGAS‐STING‐induced cytokines suppress immune response against malaria infection remain poorly understood." (PMID 35635376, 2022). "Therefore, the research and development of appropriate compounds, delivery pathways, and treatment regimens to suppress the cGAS-STING pathway will benefit patients with autoimmune and infectious diseases." (PMID 34867409, 2021). "mtDNA stress may contribute to cGAS-STING pathway activation and type I IFN responses in various pathological states, including infectious diseases, cancer, neurodegeneration and other mitochondria-related illnesses." (PMID 34016129, 2021).
metabolic disorders (22 papers, 2020 to 2026). "Although extensive research has been conducted on the role of the cGAS-STING signaling pathway in metabolic diseases, its precise association with metabolic disorders other than those induced by HFD remains to be clarified." (PMID 37762143, 2023). "This suggests that the improvement of metabolic disorder phenotype by MICT is less associated with the skeletal muscle cGAS-STING signaling pathway." (PMID 37762143, 2023). "Available evidence has demonstrated an association between DsbA-L and the cGAS–STING pathway in metabolic diseases." (PMID 34906241, 2021). "However, the improvement of MICT on the metabolic disorder phenotype is less associated with the cGAS-STING pathway, which needs to be further explored." (PMID 37762143, 2023). "Thus, we explored the association between exercise to ameliorate HFD-induced metabolic disorders and the cGAS-STING signaling pathway and compared the effects of high-intensity interval training (HIIT) and moderate-intensity continuous training (MICT)." (PMID 37762143, 2023). "However, the improvement of MICT on metabolic disorder phenotype is less associated with the cGAS-STING pathway, which needs to be further explored." (PMID 37762143, 2023). "This research highlights an unexpected metabolic function of the cGAS-cGAMP pathway and indicates the necessity of evaluating this axis in relation to physiological aging and metabolic disorders." (PMID 41593820, 2026). "Recent research has linked cytosolic mitochondrial DNA (mtDNA) with chronic aseptic inflammation by activating the cGAS-STING pathway during metabolic disorders, while autophagy activation effectively reverses this process." (PMID 39891248, 2025). "By bridging the fields of immunology and metabolism, we seek to highlight the potential of targeting the cGAS-STING axis as a novel therapeutic approach for metabolic disorders." (PMID 39669992, 2024). "Prominent research findings have substantiated the clear exacerbating impact of cGAS-STING signalling on metabolic disorders." (PMID 38164186, 2024). "Reliable evidence highlights the considerable role of the cGAS-STING signalling pathway in exacerbating metabolic disorders, even though it is essential to antiviral and antitumour defences." (PMID 38164186, 2024). "Recently, a growing number of studies have shown that the cGAS-STING signalling pathway is abnormally activated by metabolic dysfunction-induced cytosolic mtDNA release during metabolic diseases." (PMID 38129863, 2023). "The present study was based on a metabolic disorder model and investigated the cGAS-STING signaling pathway in light of these considerations." (PMID 37762143, 2023). "The current literature has demonstrated that the cGAS-STING pathway plays an important role in different metabolic diseases related to inflammation." (PMID 37762143, 2023). "Overall, the cGAS-STING pathway exerts a complex influence on the development of different metabolic diseases, not only through the promotion of inflammatory damage but also with protective functions in some respects." (PMID 37762143, 2023). "It suggests that ES and mitochondrial damage caused by metabolic stress can also activate the cGAS-STING pathway, and targeting the cGAS-STING pathway has therapeutic potential for the treatment of metabolic diseases." (PMID 33967796, 2021). "Lastly, we discuss potential mechanisms by which cGAS‒STING signaling regulates metabolism and point toward future avenues of research targeting the cGAS‒STING pathway as possible means to treat common metabolic disorders." (PMID 34665236, 2021). "Moreover, the potential contribution of cytoplasmic cGAS to many pathological processes remains uncertain, especially in neurological and metabolic diseases." (PMID 40470467, 2025).
metabolic disorders (continued). "By integrating insights from immunology and metabolism, we aim to provide a comprehensive understanding of how the cGAS-STING axis may serve as a novel target for addressing metabolic disorders and enhancing metabolic health outcomes." (PMID 39669992, 2024). "Our findings suggest that HIIT may alleviate HFD-induced metabolic disorder phenotype through the cGAS-STING signaling pathway." (PMID 37762143, 2023). "Among them, HIIT could reduce the inflammatory response and reverse the HFD-induced metabolic disorder phenotype by regulating the cGAS-STING signaling pathway in skeletal muscle." (PMID 37762143, 2023). "This raises the intriguing possibility that the cGAS-STING signaling pathway might also contribute to the development of metabolic disorders induced by factors other than high-fat diets, such as genetic factors or environmental triggers." (PMID 37762143, 2023). "Environmental triggers like oxidative stress and DNA damage, which are known contributors to metabolic disorders, have also been reported to activate the cGAS-STING pathway, suggesting its potential involvement in the pathogenesis of metabolic dysregulation beyond HFD-induced conditions." (PMID 37762143, 2023). "However, the present study found that HFD-induced metabolic abnormalities were less associated with the skeletal muscle cGAS-STING signaling pathway, so further studies on the cGAS-STING pathway and metabolic diseases need to be explored." (PMID 37762143, 2023). "To further investigate whether HFD-induced metabolic disorders are related to the skeletal muscle cGAS-STING signaling pathway, we examined the expression of key proteins of this pathway." (PMID 37762143, 2023). "This study is the first to connect Akt proteins to the cGAS–STING pathway in metabolic diseases." (PMID 34906241, 2021). "In non-ruminants, cGAS-STING has been linked to various metabolic disorders." (PMID 39891248, 2025). "However, the specific mechanism is unclear, and whether the amelioration of metabolic disorders through exercise is related to the regulation of the cGAS-STING signaling pathway remains to be further validated." (PMID 37762143, 2023). "Interestingly, we found that the skeletal muscle cGAS-STING pathway was not the underlying cause of metabolic disorders, but it did act in the improvement of metabolic disorders." (PMID 37762143, 2023). "This review focuses on the link between immune responses related to the cGAS-STING pathway and metabolic diseases and cGAS-STING interaction with other pathways for mediating signal input and affecting output." (PMID 38164186, 2024). "Our purpose is to illuminate the profound implications of the cGAS-STING pathway on metabolic equilibrium preservation and to suggest novel targets of intervention in the context of metabolic diseases." (PMID 38164186, 2024). "Although the pathogenesis of metabolic diseases remains ambiguous, the correlation between cyclic GMP-AMP synthase (cGAS)-stimulator of interferon gene (STING) and metabolic diseases has been identified recently." (PMID 37762143, 2023). "This section focuses on the molecular mechanisms of cGAS-STING-mediated inflammation, metabolic disorder, and aging in the musculoskeletal system." (PMID 37492580, 2023). "As a DNA sensor, the cGAS-STING system mediates innate host immunity by sensing exogenous DNA and metabolic diseases by sensing endogenous DNA." (PMID 38129863, 2023). "Therefore, the cGAS-STING signaling pathway may be related to exercise against metabolic diseases." (PMID 37762143, 2023). "For example, mitochondrial damage caused by lipid overload in endothelial or Kupffer cells activates the cGAS‒STING pathway and increases tissue inflammation, which is critically involved in metabolic diseases." (PMID 35084490, 2022). "Exercise training has emerged as an effective nonpharmacological strategy to suppress cGAS–STING signaling and mitigate metabolic disorder-associated organ injury." (PMID 41008530, 2025).